IL1B (interleukin 1 beta)
Diseases named in the same sentence as IL1B in open-access papers (continued):
Sharing a sentence is not in itself a finding about the gene and the disease.
rheumatoid arthritis (continued). "There have been reports that inhibiting the inflammatory response induced by IL-1β and TNF-α had protecting effect on OA progress in surgical mouse model of OA, and anti-inflammatory drugs, such as COX-2 inhibitor and diacerein, can be the common treatment for both rheumatoid arthritis and OA." (PMID 29784003, 2018). "A prototypic disease with systemic sterile inflammation characterized by elevated levels of IL-1β and TNF-α is rheumatoid arthritis (RA)." (PMID 30108259, 2018). "In the hypoxia microenvironment of rheumatoid arthritis tissue, monocytes secreted several inflammatory factors, such as IL-6, TNF-α, IL-1β and MMP-3, which contributed to the joint inflammation in RA." (PMID 29456830, 2018). "Interestingly, interleukin-1β (IL-1β) and tumor necrosis factor-α (TNF-α), which increase under pathological conditions, such as rheumatoid arthritis (RA) and osteoporosis, induce the expression of RANKL in osteoblasts and stromal cells, eventually enhancing osteoclast formation." (PMID 29104576, 2017). "Therapeutic agents that target the inflammatory cytokines IL-1β and TNF-α have been successful in treating rheumatoid arthritis (RA) and related diseases." (PMID 29284451, 2017). "However, IL-1β is not able to stimulate Has1 expression in healthy synoviocytes like in type-B synoviocytes isolated from rheumatoid arthritis patients." (PMID 25699059, 2015). "Moreover, a sustained increased expression of IL-1β and TNF-α has been reported in several cases of chronic local inflammation, as in rheumatoid arthritis and inflammatory bowel diseases, where the anticytokine therapy is very effective, reducing symptoms and slowing or arresting tissue damage." (PMID 21772667, 2011). "It is known that pro-inflammatory cytokines such as IL-1β or TNFα stimulate HMGB1 translocation into the cytoplasm and release in different cell types, although TNFα is not the main inducer of extracellular HMGB1 during synovitis in rheumatoid arthritis patients." (PMID 20799933, 2010). "and Jaspis. sp., and in an in vivo rat model of complete Freund’s adjuvant rheumatoid arthritis (RA), showed it acted as a SphK1 inhibitor in vitro and significantly improved RA symptoms measured by decreased pro-inflammatory cytokines TNF-α, IL-6, and IL-1β, swelling volume, and arthritis score." (PMID 39057418, 2024). "In rheumatoid arthritis (RA), in vivo studies have reported immunosuppressive properties of EVs that inhibit the proliferation of T lymphocytes and reduction in pro-inflammatory cytokines IL-6, TNF-α, and IL-1β." (PMID 38397121, 2024). "For instance, in the case of rheumatoid arthritis (RA), miR-146 was observed to be overexpressed in synovial tissue following stimulation with inflammatory cytokines tumor necrosis factor-alpha (TNF-α) and interleukin-1β (IL-1β)." (PMID 37685951, 2023). "Moreover, EBI3 modulates ER stress sensor inositol-requiring enzyme 1 α (IRE1α) after induced by IL-1β, and MSC-like cells coexpress EBI3 and IRE1α in rheumatoid arthritis (RA) synovial tissue." (PMID 36548354, 2022). "The pro-inflammatory cytokine interleukin 1β (IL-1β) induces the synthesis of prostaglandin E2 by upregulating cyclooxygenase-2 (COX-2) in the synovial tissue of individuals with autoimmune diseases, such as rheumatoid arthritis (RA)." (PMID 33117381, 2020). "Plenty of activated macrophages would assemble in RA joints, which could secrete some pro-inflammatory cytokines such as TNF-α and IL-1β which could accelerate the progression of rheumatoid arthritis." (PMID 30609724, 2019). "Interleukin-1β (IL-1β) and tumor necrosis factor-α (TNF-α) play a critical role in the induction and progression of rheumatoid arthritis (RA), and the efficacy of therapies targeting these two inflammatory cytokines confirms their prominent role in the disease." (PMID 26033326, 2015).
rheumatoid arthritis (continued). "Synovial cells from rheumatoid arthritis (RA) patients were treated with adiponectin or interleukin (IL)-1β for 24 hr in the presence or absence of TauCl." (PMID 20804602, 2010). "Notably, studies from the last five years have demonstrated that paclitaxel significantly inhibits the migration of rheumatoid arthritis fibroblast-like synoviocytes (RA-FLS) and reduces the production of critical inflammatory mediators, including IL-6, IL-8, and IL-1β." (PMID 41614803, 2025). "Inflammatory cytokines such as interleukin 6 (IL-6), IL-1β, and tumor necrosis factor (TNF) have been shown to be biomarkers of both acute and chronic CHIKVD, with levels of these cytokines also commonly being elevated in autoimmune arthritides such as rheumatoid arthritis (RA)." (PMID 35254128, 2022). "In synoviocytes from patients with rheumatoid arthritis, pentraxin-3 expression was synergistically induced by IL-1β and Oncostatin M (OSM), not affected by TNF or IL-1β, and dramatically reduced by TGF-β and IFN-γ." (PMID 35387000, 2021). "To determine whether IL-1β and IL-6 response modules were able to detect elevated cytokine bioactivity in vivo, we assessed the blood transcriptome of juvenile idiopathic arthritis (JIA) and rheumatoid arthritis (RA) patients." (PMID 33319166, 2021). "Increased levels of IL-1β accompany a vast number of inflammatory and non-inflammatory diseases and pathological states such as Alzheimer’s disease, cancer or rheumatoid arthritis (RA)." (PMID 32973552, 2020). "In rheumatoid arthritis (RA), a disease characterized by high levels of pro-inflammatory cytokines, NFAT5 is translocated to the nucleus and highly expressed in fibroblast-like synoviocytes (FLS) after exposure to pro-inflammatory cytokines, including TNF-α and IL-1β." (PMID 33114289, 2020). "Another interesting observation was that in these osteoarthritis cultures of synovial cells, IL-1β production was independent of TNF-α, in contrast to the situation in rheumatoid arthritis." (PMID 17177994, 2006). "S100A4 has also been shown to stimulate the production of the pro-inflammatory cytokines IL-1β, IL-6, and TNF-α from peripheral blood mononuclear cells (PBMC) isolated from patients with rheumatoid arthritis; however, these effects were not RAGE-dependent, but TLR-4-dependent." (PMID 39766257, 2024).
Insulin resistance (673 papers, 2008 to 2026). Increased resistance towards insulin, that is, diminished effectiveness of insulin in reducing blood glucose levels. "Previous study shown that IL-1β contributed to the pathogenesis of obesity-induced insulin resistance, and associated with HIF-1 production." (PMID 39891057, 2025). "NLRP3 drives the maturation and release of IL-1β and IL-18, cytokines implicated in insulin resistance and metabolic derangement." (PMID 40558557, 2025). "Mouse models with adipocyte-specific deletion of FPN or macrophage-specific CD163 deficiency exhibit exaggerated iron retention, increased IL-1β expression, and systemic insulin resistance." (PMID 40943225, 2025). "In the hyperglycemic state of diabetes, elevated ER stress leads to an increase in NLRP3 inflammasome-dependent IL-1β secretion, which causes β-cell dysfunction and promotes obesity and insulin resistance." (PMID 41208954, 2025). "Research has shown that insulin resistance is closely associated with the excessive production of pro-inflammatory cytokines, including IL-6, IL-1β, and TNF-α, which contribute to disease progression." (PMID 40136627, 2025). "Previous studies have linked elevated Il1b expression with increased adipose inflammatory responses and aggravated insulin resistance." (PMID 41019552, 2025). "Inflammatory factors produced by macrophages (TNF-α, IL-6, and IL-1β) have been shown to affect lipolysis and cause insulin resistance." (PMID 40764506, 2025). "Previous studies have shown that PC is associated with improved insulin resistance and abnormal lipid accumulation and inhibits the synthesis and release of multiple inflammatory factors, such as IL-1β and TNF-α." (PMID 39403583, 2024). "IL-1β induces the production of a wide range of cytokines and chemokines implicated in insulin resistance and type 2 diabetes such as CC-chemokine ligand 2 (CCL2), CCL3, and CXC-chemokine ligand 8 (CXCL8)." (PMID 39606781, 2024). "IL-1β can activate pro-inflammatory mediators and infiltrate macrophages, cause insulin resistance and oxidative stress, and lead to β cell dysfunction and impaired insulin secretion." (PMID 38254574, 2024). "When NLRP3 inflammasomes are overactivated, immune cells secrete excessive inflammatory factors (e.g., IL‐1β), all of which are closely associated with insulin resistance, metabolic syndrome, and diabetic progression." (PMID 38752512, 2024). "P2X7 receptors activate the NLRP3 inflammasome, and excessive activation of the NLRP3 inflammasome causes IL‐1β release, which in turn induces depressive‐like behaviors and insulin resistance in rats." (PMID 38752512, 2024). "The authentic interplay between our iPSC-Heps and M1 iPSC-Macs allowed us to identify TNFα and IL1β as the cytokines causing inflammation and insulin resistance in iPSC-Heps." (PMID 37400454, 2023). "These outcomes were in accordance with previous reports that IL-1β can regulate insulin secretion and is associated with insulin resistance." (PMID 37703108, 2023). "Macrophages in visceral adipose tissue also secrete several proinflammatory factors such as TNFα, monocyte chemoattractant protein 1 (MCP-1), and interleukin (IL)-1β, which have been implicated in the development of insulin resistance." (PMID 37935669, 2023). "Inflammasome components and IL-1β are prominently expressed in human adipose tissue, predominantly in macrophages, and are linked to insulin resistance." (PMID 37762961, 2023). "It has been reported that IL-1β elevates the risk for T2D by inducing insulin resistance and increasing β-cell apoptosis." (PMID 36902422, 2023). "Lifestyle modification aided in weight loss in obese, T2DM patients and decreased the NLRP3 and IL-1β expression and thus, in turn, the insulin resistance." (PMID 37762140, 2023). "The subsequent release of cytokines can induce insulin resistance in β-cells and secretion of IL-1β has been linked to IAPP aggregation." (PMID 35475576, 2022).
Insulin resistance (continued). "Previous research has shown that excessive production of pro-inflammatory cytokines (TNF-α, IL-1β, IL-6) causes chronic inflammation and insulin resistance." (PMID 36056976, 2022). "The increase of IL-1β level is an important risk factor for the progression of type 2 diabetes and insulin resistance." (PMID 35996380, 2022). "Overproduction of pro-inflammatory cytokines such as tumor necrosis factor alpha (TNFα) and interleukin (IL)-1β is associated with insulin resistance." (PMID 34816303, 2022). "Increased IL-1β levels cause the dysregulation of blood sugar levels by impairing pancreatic β-cells and inducing insulin resistance." (PMID 34737754, 2021). "Chronic hyperglycemia induces the production of IL-1β in pancreatic β cells which is implicated in insulin resistance as well as β cell dysfunction." (PMID 34484126, 2021). "Clinical studies suggest that IL-1β is linked to adipocyte inflammation and insulin resistance and that the factors controlling bioactive IL-1β secretion have therapeutic implications." (PMID 33546399, 2021). "Taken together, these findings suggest that insulin resistance and chronic low-grade inflammation are associated with a reduction in insulin sensitivity and increased levels of IL-1β." (PMID 34638553, 2021). "Low-grade chronic inflammation, with excess fat driving the release of proinflammatory cytokines such as TNF and IL-1β 46, is associated with adiposity, insulin resistance, hyperleptinemia, metabolic syndrome and type 2 diabetes 47–51." (PMID 33658532, 2021). "The gut microbiome seems to regulate TLR-mediated insulin resistance as experimental studies in mice deficient-TLR5 developed metabolic syndrome and insulin resistance due to dysregulation of IL-1β signaling." (PMID 33802371, 2021). "Here, we located the main components of the NLRP3 complex in skeletal muscle, and concluded that the activation of this inflammasome is linked to increments in circulating and skeletal-muscle-associated IL-1β during insulin resistance." (PMID 34638553, 2021). "The increase of IL-1β has been also associated with the development of insulin resistance and modifications of lipid components, lipoproteins and proteins, resulting in lipid metabolism disorders in CKD." (PMID 34356387, 2021). "In visceral adipose tissue, the improved insulin resistance was associated with a decreased expression of pro-inflammatory markers such as IL-1β, TNF-α, and MCP-1 and with a decreased macrophage infiltration." (PMID 32326269, 2020). "IL-1β is a significant contributor to the inflammation, insulin resistance caused by obesity, pancreatic β-cell dysfunction, and type 2 diabetes." (PMID 32397116, 2020). "These animals were fed a high fat diet (HFD), which leads to an increase in pro-inflammatory cytokines, such as IL-1β and IL-18, both of which cause high levels of systemic inflammation and insulin resistance." (PMID 32650482, 2020). "The amounts of IL-1β and IL-18 are highly implicated in the development of insulin resistance, type 2 diabetes mellitus (T2DM) and obesity-associated inflammation." (PMID 32650482, 2020). "The expression of the FA translocase in monocytes has also been shown to be associated with insulin resistance, supporting our observation for Il1b expression." (PMID 31316470, 2019). "Earlier reports showed that IL-1β is associated with defective secretion of insulin as well as the development of insulin resistance." (PMID 30937278, 2019). "In obese adipose tissue, macrophages secrete inflammatory molecules such as TNFα and IL-1β which are linked to the development of insulin resistance." (PMID 28765650, 2017). "Of the major cytokines expressed in adipose tissue from obese subjects IL-1β, IL-6, and TNFα, have been linked with the development of insulin resistance." (PMID 28957383, 2017).
Insulin resistance (continued). "Insulin resistance, a hallmark of T2D is commonly associated with systemic inflammation that is characterized by the elevated production of IL-1β and the activation of pro-inflammatory signaling pathways." (PMID 29259211, 2017). "ATM1s produce large amounts of pro-inflammatory mediators such as TNF-α, IL-1β, and IL-6, which can cause insulin resistance in adipose tissue." (PMID 29141038, 2017). "As IL-1β can also cause insulin resistance and beta cell toxicity, two aetiologies of type 2 diabetes, it is plausible that proinflammatory cytokines released by the intestine in response to different bacterial antigens affect glucose metabolism." (PMID 27577172, 2016). "Long-term treatment of adipocytes with IL-6, IL-1β, or TNFα was shown to inhibit insulin signaling and cause insulin resistance." (PMID 27066503, 2016). "Adipokines, such as tumor necrosis factor-α (TNF-α), interleukin-1β (IL-1β), and interleukin-6 are associated with development of insulin resistance and vascular disease." (PMID 25826421, 2015). "Hepatic macrophages, which consist of resident Kupffer cells and recruited bone marrow-derived macrophages, are the major cells that produce inflammatory mediators such as TNF-α and IL-1β to cause systemic insulin resistance as well as NASH23." (PMID 26603489, 2015). "In particular, the proinflammatory cytokine IL-1β can directly cause insulin resistance in insulin-sensitive cells." (PMID 26633920, 2015). "Recent several studies have demonstrated that over-nutrition and insulin resistance increase the production of proinflammatory cytokines such as IL1β and IL6, which causes pancreatic β-cell dysfunction." (PMID 25915406, 2015). "The correlation of serum IL-1β with HbA1c supports the current convention that IL-1β is strongly associated with insulin resistance and type 2 diabetes." (PMID 26633920, 2015). "Previously, it was shown that chronic exposure to TNF-α decreased insulin receptor phosphorylation in adipocytes and that increased levels of TNF-α, IL-6 and IL-1β are linked to systemic inflammation and accompany insulin resistance." (PMID 23915208, 2013). "Along with MCP-1 and F4/80, we observed higher expression levels of proinflammatory cytokines, such as IL-1β, IL-6 and TNFα, which are actively secreted by macrophages or adipocytes and cause insulin resistance." (PMID 22272317, 2012). "Selective constitutive activation of NFκB signaling in hepatocytes produced mild elevations of TNF-α and IL-1β in mouse liver and an association with severe hepatic insulin resistance." (PMID 23118937, 2012). "These M1 macrophages are associated with insulin resistance and are characterized by the expression of markers such as IL-1β, TNFα and CD11c." (PMID 23110196, 2012). "It is reported that the cytokines IL-6 and IL-1β collectively can cause insulin resistance." (PMID 41012578, 2025). "Notably, excessive IL1β signaling has been functionally linked to impaired wound closure and localized insulin resistance in both human and murine DFUs, reinforcing the pathological relevance of the inflammatory state we observed." (PMID 41255536, 2025). "To clarify the causality relationship between cytokines IL-1α, IL-1β and IL-6 from macrophages and insulin resistance, we co-cultured primary hepatocytes with BMDMs and treated them with different combinations of insulin, TSH, IL-1 blocker IL-1RA or IL-6 blocker IL-6ST." (PMID 40523992, 2025). "The NLRP3/IL-1β pathway is also implicated in inducing insulin-resistance." (PMID 39899119, 2025). "While MEFV mutations and inflammatory cytokines such as IL-1β may create a proinflammatory environment that promotes insulin resistance, additional factors such as adipose tissue dysfunction and hyperuricemia likely contribute to metabolic deterioration." (PMID 41472723, 2025).